LEP (leptin)
Diseases named in the same sentence as LEP in open-access papers (continued):
Sharing a sentence is not in itself a finding about the gene and the disease.
Insulin resistance (continued). "On the other hand, the role of leptin on insulin resistance is still not fully understood." (PMID 24455420, 2013). "Metabolic hormones (e.g., leptin, adiponectin, and glucagon), nutrient excess, systemic free fatty acids, ER stress/oxidative stress, adipose hypoxia, adipose inflammation, and so on account for the generation of insulin resistance." (PMID 23662132, 2013). "Token together with finding of GTT and ITT, the dada indicate that ER could ameliorate leptin and insulin resistance in the mice." (PMID 24312343, 2013). "We found little evidence of this on our selected population with no independent association of insulin resistance with either serum leptin or TNF-α." (PMID 23671875, 2013). "Interestingly, leptin was also significantly related with high concentrations of fasting glucose (r = 0.5227) and insulin (r = 0.2229), as well as elevated levels of insulin resistance (r = 0.3611) and circulating triglyceride (r = 0.4135)." (PMID 23986664, 2013). "Furthermore, Rimonabant corrected the insulin resistance and lowered plasma leptin, insulin and free fatty acid levels." (PMID 23712280, 2013). "The association between leptin and insulin resistance was shown to be independent of total fat mass and BMI among women in another cross-sectional study." (PMID 24455217, 2013). "Furthermore, in clinical trials, it was reported that leptin improved insulin resistance in lipoatrophic patients." (PMID 23876211, 2013). "Metabolic and hormonal parameters included glycemia, insulin, insulin resistance, and leptin." (PMID 23587409, 2013). "Understanding the pathophysiological role of leptin and insulin resistance may help address the problem." (PMID 23349940, 2013). "Our results showed BM-contained diets could reduce HFD-induced body weight gain and related adipose tissue hyperplasia, improve insulin resistance and glucose intolerance, and lower serum levels of insulin and leptin." (PMID 24358329, 2013). "When adjusted for insulin resistance (HOMA-IR) or adipocytokines (leptin, hsCRP, TNF-α) the β coefficient for BMI was attenuated in each instance >50%; consistent with both insulin resistance and inflammation mediating the association of BMI with endothelial function." (PMID 24164965, 2013). "No independent associations of insulin resistance with either Leptin or TNF-α were observed in this selected south Asian group in the two models adjusting for these parameters." (PMID 23671875, 2013). "Leptin also improves insulin resistance and reduces hyperlipidemia in lipoatrophic humans." (PMID 24209779, 2013). "Adiponectin but not leptin independently associated with HOMA-derived insulin resistance after logistic multivariate regression.Conclusion." (PMID 23671875, 2013). "In addition, the chronic exposure to a mild deficiency in dietary n-3 PUFAs potentiates the vulnerability conferred by the neonatal stress, leading to insulin resistance and altered leptin, as well as specific alterations in the peripheral fatty acids profile." (PMID 23614006, 2013). "Likewise, the leptin-to-adiponectin ratio, also reflective of insulin resistance, was essentially halved with the plant extract and decreased by 1.5-fold with the active principle." (PMID 23781256, 2013). "Alternatively, high leptin concentrations could reflect a feedback mechanism to improve insulin resistance and also ameliorate its effects on atherosclerosis in RA." (PMID 24376307, 2013). "The effect of leptin in obese and overweight population on insulin resistance was seldom reported." (PMID 23349940, 2013). "The leptin/adiponectin ratio is a marker of insulin resistance and the metabolic syndrome." (PMID 23509614, 2013). "Therefore, the downregulation of OBRL in obese subjects seems to be only a consequence of the high leptin levels, whereas leptin should be considered a determinant factor in worsening of insulin resistance in obese adults." (PMID 24454366, 2013).
Insulin resistance (continued). "In a population of relatively lean adult Chinese men and women, increased leptin levels were associated with insulin resistance and prediabetes, although the causal relation was not revealed." (PMID 23781317, 2013). "Those receiving exercise intervention alone (HE) maintained their pre intervention body weight (−0.28±0.75 g) and level of adiposity with serum cholesterol and insulin resistance remaining comparable to HH males (p>0.05) however, had a significant reduction in serum leptin levels (p<0.05)." (PMID 23977045, 2013). "It suggests that predictors of leptin expression under insulin resistance status might differ, however to draw a conclusion, further investigation is needed." (PMID 23853618, 2013). "Infusion of leptin is able to reverse the phenotype of hepatic steatosis and insulin resistance." (PMID 23554788, 2013). "Expression of SOCS-3 amplifies along with the increase in fat mass and abdominal adiposity during aging, as well as an increase in insulin resistance, suggesting that it could be a mediator of leptin resistance in aging individuals." (PMID 24455217, 2013). "Furthermore, leptin related to homeostasis model assessment for insulin resistance (HOMA-IR) (r = 0.422, P = 0.006) was observed only in T2DM subjects." (PMID 23853613, 2013). "The peptide hormone insulin is produced by beta cells in the pancreas and released in response to hyperglycemia, which is associated with insulin resistance, aberrant glucose metabolism, chronic inflammation, and the production of other metabolic hormones, such as IGF-1, leptin, and adiponectin." (PMID 24280167, 2013). "However, data on the effect of leptin in obese and overweight population on insulin resistance are scarce, other than one study focusing in diabetic women." (PMID 23349940, 2013). "However in combination, ASP + MSG significantly elevated all these parameters, and doubled fasting serum leptin and TNFα, whilst promoting insulin resistance and hepatic steatosis." (PMID 23783067, 2013). "The question addressed was whether adiponectin alone or in combination with leptin had an effect on dyslipidemia and insulin resistance." (PMID 23533722, 2013). "Sympathetic activation can be triggered by reflex mechanisms as arterial baroreceptor impairment, by metabolic factors as insulin resistance, and by dysregulated adipokine production and secretion from visceral fat with a mainly permissive role of leptin and antagonist role of adiponectin." (PMID 24288531, 2013). "Furthermore, centrally administered leptin effectively decreases the rate of fat accumulation, hyperglycemia, insulin resistance, hyperinsulinemia, and progression to metabolic syndrome in obese rodents." (PMID 22518191, 2012). "We have found a reduction of vimentin, a mesenchymal marker in visceral fat depot, which could exacerbate inflammation and partial insulin resistance observed after chronic leptin treatment." (PMID 23056516, 2012). "In addition, a direct effect of leptin has been shown in clinical studies where induced hyperleptinemia contributes to increase insulin resistance, whereas interruption of treatment ameliorates the sensitivity to insulin." (PMID 23056516, 2012). "In addition, subjects carrying Gly16 allele regardless of their BMI had greater waist and hip circumference, W/H ratio, plasma lipids, leptin, glucose level, and insulin resistance as judged from the HOMA-IR, compared to those with the wild-type allele." (PMID 23056045, 2012). "Recent studies have reported the leptin/adiponectin ratio is correlated with body mass index and may be a useful biomarker for inflammation, insulin resistance, and atherogenesis." (PMID 22778500, 2012). "Since it has become increasingly clear that the altered endocrine activity of adipose tissue is associated with insulin resistance, we measured the plasma concentration of leptin and adiponectin, two central regulators of insulin resistance that are involved in maintaining energy homeostasis." (PMID 23146593, 2012).
Insulin resistance (continued). "Therefore, the aim of our study was to assess the correlation of the dynamics of insulin resistance with leptin and adiponectin, as well as anthropometric measures of body fat during puberty in a large sample of Chinese children and adolescents." (PMID 23316228, 2012). "This elevation in leptin may be due in part to insulin resistance but a direct cardioprotective effect of leptin also has been proposed." (PMID 22518191, 2012). "In all cases, since adiponectin levels tended to increase and leptin/adiponectin ratio (an indicator of insulin resistance) significantly decreased with ingestion of L. laricina, proinsulin-resistant systemic factors seem to be decreased and insulin sensitivity improved." (PMID 22888363, 2012). "In addition to leptin, mammalian adiponectin secreted from adipose tissue profoundly affects insulin resistance and type 2 diabetes." (PMID 22935001, 2012). "Fourth, smoking habit or adipokines such as leptin may influence the distribution of regional abdominal adiposity and insulin resistance." (PMID 22301198, 2012). "Leptin and adiponectin have been shown to play an important role in insulin resistance." (PMID 22474499, 2012). "In addition, alterations in leptin secretion and elevated ghrelin in sleep-deprived subjects were reported to contribute to impaired glucose tolerance and insulin resistance through weight gain." (PMID 22829819, 2012). "While strong tendencies are apparent in the prevention study, insulinemia and leptin/adiponectin ratio were significantly decreased in the treatment study (especially with the highest dose of L. laricina), suggesting improvement of systemic insulin resistance." (PMID 22888363, 2012). "Therefore, SOCS3 is a single molecule that mediates both leptin and insulin resistance due to its ability to down-regulate leptin and insulin signaling." (PMID 23115649, 2012). "A high leptin:adiponectin ratio has been correlated with increased risk for developing insulin resistance in obese and non-obese individuals." (PMID 23056418, 2012). "We found that leptin was an independent determinant of the pubertal insulin resistance." (PMID 23316228, 2012). "The current results also showed complicated nonlinear associations between low serum amylase and high HOMA-R and high leptin, as low serum amylase was associated with severe insulin resistance but not moderate insulin resistance." (PMID 22748134, 2012). "Also, leptin is also reported to be related to insulin resistance and high C-reactive protein levels, both of which have been shown to be related to CKD." (PMID 22666590, 2012). "In addition, MetS patients exhibited lower levels of adiponectin compared to control subjects, although leptin levels were similar in both groups, supporting insulin resistance within the MetS patients." (PMID 22110764, 2011). "Leptin and adiponectin respond to increasing adiposity in a reciprocal manner, and the plasma leptin to adiponectin ratio may be a potential measure of insulin resistance." (PMID 21331287, 2011). "However, among the adipose-derived mediators, leptin can be envisioned as a sex-independent discrimination marker of adiposity degree and, at least in girls, a reliable indicator of the systemic insulin resistance as estimated by HOMA-IR." (PMID 21365005, 2011). "Finally, in this cohort of prepubertal children, we found that leptin, at least in girls, was an independent determinant of the basal insulin resistance, and, independently from sex, it emerged as a stronger contributor of HOMA-IR than HMW adiponectin." (PMID 21365005, 2011). "In the present study, SHR showed features of the human metabolic syndrome, such as overweight, hyperglycaemia, hyperinsulinemia, insulin resistance, dyslipidemia, and increased circulating concentrations of leptin, which confirm data reported by our group and others." (PMID 20592755, 2010).
Insulin resistance (continued). "However, no such studies have been performed to date in the WAT of obese patients with type 2 diabetes, who can be characterised by similar whole body insulin resistance, but lower plasma leptin levels, as compared to matched non diabetic obese subjects." (PMID 20426869, 2010). "Thus the leptin to adiponectin ratio, a novel marker for insulin resistance, exhibited a significant decrease." (PMID 21179199, 2010). "High circulating levels of TNF-α, IL-6, and leptin are recognized as markers of insulin resistance." (PMID 21403905, 2010). "Our findings suggest that the mechanism by which the OPN KO mice are protected from HFD-induced insulin resistance involves reduced leptin expression, decreased hypertrophy of adipocytes, and suppression of inflammatory macrophage infiltration and cytokine secretion in adipose tissue." (PMID 21103061, 2010). "This indicates that the increase in SAT AEA levels (and, possibly, also OEA and PEA), observed in OBT2D subjects was more related to the lower leptin levels than to the level of whole body insulin resistance, which was instead similar between the two obese groups." (PMID 20426869, 2010). "Glucocorticosteroids may have a stimulating effect on leptin via the induction of insulin resistance, as glucose and insulin are also able to induce leptin expression." (PMID 19344528, 2009). "The plasma leptin:adiponectin ratio is another valid index for insulin resistance." (PMID 19606226, 2009). "Leptin concentrations tended to be higher in obese subjects with insulin resistance." (PMID 18553029, 2008). "It has been reported that Dgat2 is regulated by Leptin and is involved in insulin resistance." (PMID 18522719, 2008). "While cytokines like TNF–alfa and IL1 have a profibrotic effect and determine insulin resistance, adipocyte hormones have an opposite result;leptin and visfatin improve insulin resistance, while adiponectin and resistin increase it and have an anti–fibrosis effect." (PMID 20108479, 2008). "There was a trend towards higher leptin concentration in obese individuals with insulin resistance." (PMID 18553029, 2008). "Leptin may be a marker of risk of CHD, at least in males, and contributes to the CHD risk profile in subjects with insulin resistance." (PMID 17617917, 2007). "We hypothesised that short-term glucocorticoid treatment among healthy individuals would cause insulin resistance, with coordinated increases in TNF alpha, leptin and ghrelin, and decreases in adiponectin." (PMID 16965635, 2006). "Our data do not support a role for TNF alpha, ghrelin, leptin or adiponectin in the insulin resistance associated with short-term glucocorticoid treatment." (PMID 16965635, 2006). "However, it may contribute to more aggressive cancer progression over time due to the metabolic conditions that it induces, such as chronic inflammation, insulin resistance, hyperglycemia, hormonal imbalance, and leptin and adipokine dysregulation." (PMID 40003658, 2025). "Additionally, we examined whether NPT levels correlate with other hormonal factors—such as insulin, leptin, or ghrelin —which play key roles in the pathogenesis of insulin resistance." (PMID 41007299, 2025). "However, leptin had a weak positive correlation with insulin resistance (r=0.4895, P=0.0543)." (PMID 40862455, 2025). "The ASE of SDF2, observed at 70:30 in the hypothalamus and 63:37 in the hippocampus in our study, along with its identification as a pig brain eQTL, suggests it may help mitigate ER stress, preserve leptin signaling, and reduce inflammation and insulin resistance." (PMID 40969342, 2025). "Additionally, higher leptin levels and increased adipocyte size could promote inflammatory responses in adipose tissue, further exacerbating insulin resistance." (PMID 40057491, 2025). "Additionally, sugar-sweetened beverages (SSBs) are associated with increased insulin resistance, higher insulin levels, and elevated leptin levels, particularly in men and non-overweight women." (PMID 40873447, 2025).
Insulin resistance (continued). "The results demonstrated that maternal insulin resistance and hyperinsulinemia impair endocrine pancreas development and lead to metabolic disturbances in offspring, including higher postnatal glucose, insulin, leptin, glucagon, and GLP-1 levels, along with reduced β-cell area and proliferation." (PMID 41007299, 2025). "Furthermore, chronic exposure to UPFs has shown ties to impaired dysregulation of the HPA axis and neuroendocrine imbalances, including insulin resistance and leptin dysfunction, which might interfere with stress regulation and emotional processing." (PMID 40362891, 2025). "Leptin has been reported to block insulin secretion in pancreatic β-cells, whereas leptin resistance was found to provoke the continuous secretion of insulin, which may promote insulin resistance." (PMID 40095937, 2025). "Furthermore, the chronic state of inflammation, characterized by increased levels of C-reactive protein, inflammatory cytokines, resistin, leptin, and adiponectin, affects insulin resistance, leading to the exhaustion of pancreatic beta cells and impairing the maintenance of normoglycemia." (PMID 40299945, 2025). "Moreover, studies found that smokers had lower levels of leptin than non-smokers, while another study hypothesized that nicotine might directly affect insulin resistance by raising the levels of leptin in the blood." (PMID 40283443, 2025). "In addition to leptin dysregulation, several other contributors—including insulin resistance, mitochondrial dysfunction, oxidative stress, proinflammatory adipokines such as MCP-1 and resistin, and gut microbiota-derived endotoxins—are implicated in driving peripheral and central inflammation." (PMID 40521397, 2025). "Therefore, in the context of insulin therapy in T1DM, it may further raise leptin levels, dysregulate metabolic control, increase appetite, facilitate weight gain, and develop insulin resistance." (PMID 40277935, 2025). "Ostarine has been shown to reduce the secretion of leptin and adiponectin from white adipocytes, while low levels of leptin can intensify de novo lipogenesis in the liver and promote lipid accumulation in muscles, affecting insulin production in the pancreas and contribute to insulin resistance." (PMID 38059982, 2024). "From the cardiometabolic parameters assessed, insulin resistance and circulating leptin levels were significantly higher in the MUO group than the MHO group, suggesting that the presence of leptin resistance maybe central to the worse metabolic profile observed in the MUO phenotype." (PMID 39145170, 2024). "Furthermore, the percentage of Th1 cells producing IFN-γ has been shown to exhibit a positive correlation with insulin resistance in obese patients, as evidenced by elevated levels of leptin, insulin, and homeostatic model assessment of insulin resistance (HOMA-IR) values." (PMID 39148730, 2024). "In addition to the adiponectin-to-leptin ratio, other mechanisms may contribute to systemic insulin resistance in individuals with severe COVID-19." (PMID 37934800, 2024). "Moreover, PGA-K reduced the levels of insulin resistance markers, including insulin and leptin." (PMID 38542720, 2024). "In addition to lipid and glucose abnormalities, patients with SS have increased body fat, insulin resistance (IR), coagulation abnormalities, increased leptin concentration, low-grade inflammation, and endothelial dysfunction that predispose them to cardiovascular diseases." (PMID 36742387, 2023). "In addition to increased nocturnal sympathetic activity, factors such as reduced renal sodium excretion, leptin and insulin resistance, salt sensitivity, endothelial dysfunction and sleep breathing disorders affect the non-dipping and reverse dipping BP pattern." (PMID 37508741, 2023).